SCN1A (sodium voltage-gated channel alpha subunit 1)
Diseases named in the same sentence as SCN1A in open-access papers (continued):
Sharing a sentence is not in itself a finding about the gene and the disease.
epilepsy (continued). "Genetic models of epilepsy, such as sodium channel protein type 1 subunit alpha (SCN1A) knockout mice, provide critical insights into the mechanisms underlying inherited epileptic syndromes, including Dravet syndrome." (PMID 41333733, 2025). "Minderhoud and co‐authors conducted a study regarding gastrointestinal and eating problems in individuals with SCN1A‐related epilepsies, the majority of whom had Dravet syndrome." (PMID 39503590, 2025). "Identified in five DS and GEFS+ cases, this mechanism not only validates non-coding variants as disruptors of core RNA processing machinery but also highlights splicing regulatory elements as potential therapeutic targets for SCN1A-related epilepsies." (PMID 40772259, 2025). "Scn1a+/- mice show minimal phenotypes on 129 backgrounds but severe epilepsy with premature death on C57BL/6J backgrounds." (PMID 41151066, 2025). "EPBL-0016 with Dravet syndrome has a large de novo deletion encompassing several sodium channel coding genes including the well-known epilepsy gene SCN1A." (PMID 40565278, 2025). "To date, few studies, particularly small case series, have explored the effectiveness of highly purified CBD in monogenic epilepsies other than TSC and DS caused by SCN1A pathogenic variants." (PMID 40126049, 2025). "All Scn1a+/- mice experienced seizures induced by hyperthermia, which provided convenience for studying the relationship among epilepsy of DS, CO2, and ASIC1a." (PMID 40217340, 2025). "In SCN1A-related epilepsies, the most common abnormalities were cerebral atrophy (15.8%) and hippocampal abnormalities (6.1%)." (PMID 41573391, 2025). "Significance: In both the epilepsy panel and WES groups, variants in sodium channel proteins, specifically in the SCN1A, SCN8A, and SCN9A genes, were found to have a high frequency." (PMID 40565516, 2025). "Genes like SCN1A and TSC2, identified in this study, are associated with syndromes like DS and tuberous sclerosis complex, both featuring epilepsy and developmental impairments." (PMID 39906551, 2024). "Genetic variants of NaV1.1 (SCN1A), NaV1.2 (SCN2A), NaV1.3 (SCN3A), and NaV1.6 (SCN8A) sodium channels are involved in a broad spectrum of diseases, including several types of epilepsy." (PMID 37654020, 2024). "Health-related quality of life and disease features were assessed cross-sectionally in participants with a SCN1A-related seizure disorder, categorized per age group for Dravet syndrome, and longitudinally over seven years follow-up (2015–2022)." (PMID 39239151, 2024). "The SCN1A gene, located on chromosome 2q24.3, holds pivotal significance in the pathogenesis of epilepsy." (PMID 39119390, 2024). "The genotype–phenotype correlation of SCN1A-related seizure disorders still remains uncertain; however, recent data from extensive cohort studies seem to be giving us some clues." (PMID 38785537, 2024). "This investigation aims to delve into the influence of SCN1A and SCN2A gene polymorphisms on the effectiveness of VPA in managing epilepsy among the Han Chinese population." (PMID 38837984, 2024). "We aimed to examine the relationship between SCN1A, GABRA1 and ABCB1 polymorphism and drug response in epilepsy children in Vietnam." (PMID 38674283, 2024). "This occurs even in cases of monogenic epilepsy, such as Dravet syndrome (associated with SCN1A variants), developmental epileptic encephalopathies (DEE), and other forms of epilepsy associated with intellectual disability." (PMID 38637998, 2024). "Unfortunately, the treatment of SCN1A-related epilepsies is unsettling and includes aggressive seizure management while the developmental regression is persistent." (PMID 39119390, 2024). "This study explored the expression of long non-coding RNAs (lncRNAs) related to SCN1A in brain tissues of pediatric epilepsy patients, aiming to identify potential targets for therapy." (PMID 38920691, 2024).
epilepsy (continued). "For the Scn1a gene knock-in and knock-out models, both approaches are used to study epilepsy, particularly Dravet syndrome." (PMID 39452036, 2024). "This study has provided a comprehensive overview of the evolution of HRQoL and other disease features in SCN1A-related seizure disorders." (PMID 39239151, 2024). "Variability in seizure phenotypes among SCN1A-mutated patients suggests potential interactions with other ion channel genes, such as SCN2A and SCN8A, underscoring the polygenic complexity of SCN1A-related epilepsies." (PMID 39906551, 2024). "The role of genetic variations, specifically in sodium channels encoded by SCN1A and SCN2A genes, in influencing the effectiveness of VPA in treating epilepsy is still debated." (PMID 38837984, 2024). "DEE has further been divided into clinical subtypes such as myoclonic atonic epilepsy, Dravet syndrome, epilepsy of infancy with migrating focal seizures, and early-onset SCN1A DEE." (PMID 39119390, 2024). "Meanwhile, sodium channel blockers like carbamazepine, phenytoin, and lamotrigine can be contraindicated in DS, as well as in other SCN1A-related seizure disorders." (PMID 39165469, 2024). "Genetic variants related to ion channels (e.g., SCN1A), calcium signaling (e.g., CALHM1), or neurotransmitter actions (e.g., GABBR1, 5-HTT) have all been linked to common epilepsies, including TLE." (PMID 38927072, 2024). "There were 33 individuals included in the SCN1A gene group, 10 of which had epilepsy and HM together, whereas 3 only suffered from epilepsy." (PMID 38273253, 2024). "ASOs also increased the expression of wild-type sodium voltage-gated channel alpha subunit 1 (SCN1A) gene, which is known to be mutated in Dravet syndrome, a rare genetic brain disease characterised by lifelong epilepsy." (PMID 38841098, 2024). "In contrast, when crossed with C57BL/6J (B6) mice, the resulting [B6 × 129]F1.Scn1a+/− mice recapitulated core features of Dravet syndrome, including spontaneous seizures and epilepsy, and a high incidence of SUDEP-like death in the first month of life." (PMID 38862622, 2024). "Predictors of worse long-term developmental outcome included poorer baseline language ability (P < 0.001), more severe baseline epilepsy severity (P = 0.003) and a worse SCN1A genetic score (P = 0.027)." (PMID 38229878, 2024). "In the present study, we aim to find the association of SNPs in three genes including SCN1A, GABRA1 and ABCB1 in Vietnamese children affected by epilepsy." (PMID 38674283, 2024). "SCN1A mutations have been discovered in both pure FHM families and FHM patients with other disorders, such as epilepsy and intermittent daily blindness." (PMID 38674378, 2024). "Among the epilepsy panel findings in our cohort, we were only able to find functional studies for the two known disease-associated variants in the genes EPM2A and SCN1A." (PMID 38756210, 2024). "This study provides an overview of the evolution of HRQoL across the lifespan, by performing a cross-sectional and longitudinal assessment of a cohort of SCN1A-related seizure disorders." (PMID 39239151, 2024). "Such modifier genes have been proposed for other Mendelian disorders, such as monogenic cases of autism spectrum disorder, SCN1A-related epilepsy, and cystic fibrosis." (PMID 38298782, 2024). "Because SCN1A is needed for neurons to fire and spread action potentials, the genes that code for this channel are thought to play a significant role in epilepsy." (PMID 39861097, 2024). "Five single nucleotide polymorphisms (SNPs), including SCN1A (rs10188577, rs2298771, rs3812718) and SCN2A (rs2304016, rs17183814), were genotyped in 233 epilepsy patients undergoing VPA therapy." (PMID 38837984, 2024). "Genetic variants in SCN1A, SCN2A, and SCN1B, encoding voltage-gated sodium channels, contributed to early-onset epilepsy." (PMID 36835631, 2023).
epilepsy (continued). "Although SCN1A is firmly established as a gene that is crucial to the pathophysiology of epilepsy, the relationship between genotype and phenotype is complex and at times counterintuitive." (PMID 37139072, 2023). "Here, we showed that reduction of Kcnt1 expression is protective in mouse models of Scn1a and Scn8a epilepsy." (PMID 37901435, 2023). "SCN1A, SCN2A, SCN3A, SCN8A, SCN9A, SCN11A, and SCN1B sodium channel gene mutations were intimately associated with epilepsy and displayed significant heterogeneity in pathogenesis and clinical symptoms." (PMID 38174099, 2023). "Rarely, SCN1A variants are implicated in other forms of DEE including myoclonic astatic epilepsy, epilepsy of infancy with migrating focal seizures, West Syndrome and Lennox–Gastaut Syndrome." (PMID 37139072, 2023). "This has been confirmed in the Scn1a+/− mouse model that shares both epilepsy and ASD-like social impairment phenotypes where the prosocial benefits were found at 1/10th that of the antiepileptic dose." (PMID 37397463, 2023). "Loss-of-function (LOF) mutations of the sodium channel gene SCN1A and GOF mutations of the potassium channel gene KCNT1 can also cause epilepsy." (PMID 37901435, 2023). "The phenotype of SCN1A channelopathies has expanded beyond epilepsy to include a rare form of hemiplegic migraine often inherited in autosomal dominant fashion with incomplete penetrance, known as familial hemiplegic migraine (FHM)." (PMID 37139072, 2023). "The anti‐seizure effect of E2730 against multiple seizure types was further investigated in other epilepsy animal models, such as 6 Hz‐44 mA psychomotor seizures in mice, amygdala kindling rats, Fmr1 KO mice, and Scn1a+/− mice." (PMID 37052238, 2023). "Cacna1g has also been identified as a genetic modifier of epilepsy in the Scn1a+/− mouse model of Dravet syndrome." (PMID 37082241, 2023). "Our results showing ictal vocalizations in Scn1a+/− mice during GTCS are consistent with the ictal cry common in epilepsy patients with generalized tonic–clonic or focal seizures." (PMID 36811143, 2023). "These were mainly patients with SCN1A-related epilepsy (7/15), who have benefited from the introduction of first-line and add-on therapy for Dravet syndrome and/or halting carbamazepine for focal seizures." (PMID 38250573, 2023). "This strategy has been thereafter applied in several other studies, including more on the SCN1A gene, but also in other models of epilepsy, like in a model of KCNQ2 encephalopathy." (PMID 37719765, 2023). "For example, KCNQ2, KCNQ3, SCN1A, SCN2A, and SCN8A are associated with phenotypes ranging from self-limited epilepsies with normal developmental outcome to intermediate severity conditions to drug-resistant epilepsies with profound developmental impairment." (PMID 37596007, 2023). "The pH of saliva and urine was chronically high in patients with SCN1A-related epilepsy, and urine pH was higher in patients with seizures and with Dravet syndrome." (PMID 36237607, 2022). "The results can be used to define the phenotypic spectrum as well as provide a scientific basis for precision-based clinical treatment and genetic counseling for SCN1A-related seizure disorders." (PMID 35571373, 2022). "This study showed a significant difference in clinical prognosis between the epilepsy caused by ATP6V0C mutations and Dravet syndrome caused by SCN1A mutations." (PMID 35600075, 2022). "This is highlighted in Dravet syndrome (DS), a treatment-resistant form of epilepsy with a high risk for SUDEP, where loss-of-function mutations have been reported in the SCN1A gene, which encodes a subtype of voltage-gated sodium channel in the brain." (PMID 35893283, 2022).
epilepsy (continued). "The sodium channel genes SCN1A and SCN2A encode the α subunit of voltage-gated sodium channels, and thus, mutations in these genes can be potential source of drug resistance in epilepsy." (PMID 35136380, 2022). "Rare microduplications at 17q12 are associated with epilepsy, including familial FS/GEFS + that is also often caused by SCN1A variants." (PMID 35606653, 2022). "Successful use of ASOs for severe epilepsies has been reported in preclinical models of SCN1A, SCN2A, and SCN8A encephalopathy." (PMID 36173683, 2022). "This corresponds with human clinical data demonstrating hippocampal involvement in patients with SCN1A-related seizure disorders." (PMID 35212623, 2022). "Future experiments on co-culture of both excitatory and inhibitory neurons to directly measure E/I ratio with the same genetic background is clearly needed to draw a firm conclusion on the roles of SCN1A LOF and GOF mutations in epilepsy." (PMID 35359577, 2022). "The red square represents patients with SCN1A-related epilepsy, and the blue triangle represents the control group." (PMID 36237607, 2022). "We will first consider therapies for SCN1A before addressing precision therapies for SCN2A/8A-related epilepsy because similar considerations regarding sodium channel blockade apply to these three conditions." (PMID 35250833, 2022). "The pH of saliva and urine was chronically higher in patients with SCN1A-related epilepsy than in the control group." (PMID 36237607, 2022). "Scn1a+/− mice on the 129S6/SvEvTac strain have no overt phenotype and a normal lifespan, while [C57BL/6Jx129]F1.Scn1a+/− mice have severe epilepsy with high rates of premature death." (PMID 35606653, 2022). "In other experiments, when administered to animals mutant for Scn1a+/−, a common epilepsy gene, CBD improved social behavior and reduced hyperlocomotion." (PMID 35629320, 2022). "This is the first study to evaluate the pH of saliva and urine in SCN1A-related epilepsy patients, which would be the first step in the application of preventive therapeutic strategies for patients with SCN1A-related epilepsy." (PMID 36237607, 2022). "It has also been demonstrated that the PI3K/Akt/mTOR pathway is overactivated in different ASD and epilepsy mouse models including the Scn1a ± mouse model." (PMID 34980259, 2022). "However, epilepsy genes with undefined inheritance patterns, including genes with de novo mutations, have also been reported that are de novo associated with autosomal dominant genetic disorders as observed in SCN1A mutations, typically in Dravet syndrome and in epileptic encephalopathies." (PMID 36142719, 2022). "We propose that the rs2169312, rs13405797, rs2162600 of SCN1A and rs353139 of SCN2A are risk factor for epilepsy among individual with history of febrile seizure." (PMID 35801810, 2022). "Voltage-gated sodium channels (VGSCs) play a critical role in generation of action potentials, SCN1A, SCN2A, SCN3A, SCN8A and SCN1B have been identified to be associated with a spectrum of epilepsy phenotypes and neurodevelopmental disorders." (PMID 36006933, 2022). "A number of in-frame deletion variants in an epilepsy-associated gene SCN1A, encoding voltage gated sodium channel alpha unit 1.1 (Nav1.1), have been reported in public database." (PMID 35359575, 2022). "SCN1A had been one of the first recognized “epilepsy genes” and is now one of the most frequently identified causes of DEEs." (PMID 36231081, 2022). "The most common genes for epilepsy with genetic photosensitivity are SCN1A and CHD2, and the most common syndromes are PME and Dravet syndrome." (PMID 36034301, 2022). "Mice with heterozygous targeted deletion of Scn1a (Scn1a+/−) are a well-validated model and recapitulate core features of Dravet syndrome, including epilepsy and sudden unexpected death following a seizure in otherwise healthy animals (SUDEP-like)." (PMID 35606653, 2022).
epilepsy (continued). "In the following part of this article, we review what has been learned from SCN1A epilepsy models and the possibilities and advantages of the use of patient-specific induced pluripotent stem-cell-derived (iPSC-derived) neurons and 3D organoid models." (PMID 36231081, 2022). "The saliva and urine pH were chronically high in this series of patients with SCN1A-related epilepsy." (PMID 36237607, 2022). "These cells share neuronal genes expressed in central excitatory neurons such as Kcna1, Kcnq2, Kcnq3, Scn1a, Scn8a, genes that are relevant to epilepsy." (PMID 36192157, 2022). "In this study, the association of sodium channel genes SCN1A and SCN2A polymorphisms with drug-resistant epilepsy was studied." (PMID 35136380, 2022). "SCN1A is the most clinically relevant gene in a wide spectrum of epilepsy phenotypes ranging from febrile seizures to Dravet syndrome (DS)." (PMID 35663268, 2022). "The p.Phe218.Leu mutation of SCN1A (2q24.3; MIM #182389) gene is known as a genetic factor in general epilepsy with febrile seizures plus type 2 (GEFSP2; 2q24.3; MIM #604403)." (PMID 35740751, 2022). "This study investigated several genetic variants of SCN genes (SCN1A, SCN2A, SCN3A, SCN1B, SCN2B, SCN3B and SCN8A) and their association with epilepsy risk; these genes have been studied in this regard and conflicted results were reported." (PMID 35801810, 2022). "VGSCs are known to play an important role in neuronal excitability and epilepsies; especially mutations in VGSC subunit genes such as SCN1A, SCN2A, SCN3A, and SCN8A have been found to cause human epilepsies." (PMID 35860491, 2022). "Indeed, Scn1a, the gene that encodes NaV1.1, is referred to as a ‘super culprit’ gene, with over 1000 associated mutations that lead to abnormal brain function, resulting in brain disorders such as epilepsy and migraine, as well as neurodivergent phenotypes, such as autism spectrum disorder." (PMID 36278870, 2022). "Seven children were patients with SCN1A-related epilepsy, including two Dravet syndrome patients (patients 1 and 7)." (PMID 36237607, 2022). "The pH of saliva and urine was higher in patients with SCN1A-related epilepsy than in the healthy group." (PMID 36237607, 2022). "This case-control (100 control: 101patients) study evaluated the association of sodium channel genes SCN1A and SCN2A with drug-resistant epilepsy." (PMID 35136380, 2022). "Hyperthermia is contraindicated for heat-sensitive epilepsy (SCN1A-related epilepsy such as Dravet syndrome)." (PMID 36237607, 2022). "In order of population prevalence, SCN1A, SCN2A, and SCN8A are the four voltage-gated sodium channel genes that are most commonly associated with epilepsy." (PMID 35250833, 2022). "A prospective controlled observational study with a 1:1 ratio was conducted on seven patients with SCN1A-related epilepsy and seven healthy children of the same family, gender, and age but without a history of seizures." (PMID 36237607, 2022). "Sodium channel blockers are being discontinued as a choice of treatment for the management of SCN1A-related seizure disorders due to their proven exacerbating effects in the presence of such mutations." (PMID 33841294, 2021). "Mutations in SCN1A and PCDH19 are well known to cause several types of epilepsy that are associated with FS." (PMID 33407677, 2021). "Our data demonstrates that 1b is an essential and important regulator of Scn1a expression and highlights a potential target for epigenomic intervention in SCN1A-related epilepsies." (PMID 33910599, 2021). ": This meta-analysis will summarize the effects of SCN1A and SCN2A gene polymorphisms on VPA response in children with epilepsy." (PMID 34011048, 2021).